ATF4 (activating transcription factor 4)
Diseases named in the same sentence as ATF4 in open-access papers (continued):
Sharing a sentence is not in itself a finding about the gene and the disease.
neuroblastoma (continued). "Similarly, N‐Myc and ATF4 collectively drive the metabolic reprogramming in neuroblastoma cells, leading to dependency on the serine–glycine–one‐carbon metabolic pathway." (PMID 32310340, 2020). "Likewise, blockade of essential amino acid transport triggers the GCN2‐eIF2α‐ATF4 pathway and inhibits neuroblastoma tumor growth, which is concomitant with attenuated translation of MYC and MYCN mRNAs." (PMID 32310340, 2020). "Therefore, the role of ATF4 in neuroblastoma cells with elevated MYC varies depending on the condition." (PMID 32310340, 2020). "In addition, MYC-mediated cell death that occurs upon glutamine deprivation of neuroblastoma cells has been shown to be facilitated by the ATF4 pathway." (PMID 28950000, 2017). "Thus, we took another approach, which was to engineer the SK-N-AS human neuroblastoma cell line with inducible expression of shRNA to ATF4." (PMID 23144714, 2012). "In addition, to counteract nutritional stress due to glutamine deficiency, the murine neuroblastoma cell line N18TG2 promoted lactate synthesis; nevertheless, in a manner dependent on activating transcription factor 4 (ATF4), the cells entered quiescent-metabolic and -proliferative phases." (PMID 36499405, 2022). "Our findings supported that emodin significantly inhibited ROS generation and decreased the zinc-induced CHOP, GADD34, and ATF4 protein overexpression, implying that emodin may protect against zinc-induced neurotoxicity in neuroblastoma SH-SY5Y cells by blocking the production of ROS and ER-stress." (PMID 31023967, 2019). "MYCN, ATF4, and KDM4C all contribute to transcriptional upregulation of GOT1, GOT2, GPT, GPT2, and PSAT1 in neuroblastoma cells." (PMID 36077650, 2022). "Together, these findings suggest that MYCN, ATF4, and KDM4C work together to promote glutamine uptake and metabolism in MYCN-amplified neuroblastoma cells to meet the biosynthetic demands of cell growth and proliferation." (PMID 36077650, 2022). "PLK-1, CDK-1, PIK3CA, ATF4, TEAD4 and ALYREF could enhance MYCN protein stability and sustain MYCN expression in neuroblastoma." (PMID 35820898, 2022). "Both ATF4 and CHOP mRNA and protein levels were increased in human hepatocytes and neuroblastoma cells exposed to high levels of FFAs, suggesting that FFAs may induce ATF4 expression." (PMID 36139021, 2022). "Another example; ATF4 is involved in the induction of serine/glycine biosynthesis in different cancer types, e.g., ER-negative breast cancer, NSCLC, or neuroblastoma, and promotes cancer cell survival under stress conditions, e.g., hypoxic and nutrient-deprived environments." (PMID 33801846, 2021). "In neuroblastoma, MYCN and ATF4 act through a positive feedback loop." (PMID 33801846, 2021). "To determine whether DR5 transcription is regulated by ER stress in neuroblastoma cells, we examined the ER stress marker proteins BIP, ATF4 and CHOP." (PMID 29113358, 2017). "In the present study, we show that treatment of neuroblastoma cells with Flv induces Sig-1R expression by increasing ATF4 translation directly, through its own activation, without involvement of the PERK pathway." (PMID 25032855, 2014). "In addition, manual curation highlighted ATF4 upregulation in MYCN-amplified compared to non-MYCN-amplified neuroblastoma cell lines, even with less induction (FC 1.77, p-value 0.047)." (PMID 37835497, 2023).
gastric cancer (28 papers, 2012 to 2025). A primary or metastatic malignant neoplasm involving the stomach. "This study provides a new understanding of the critical underlying mechanism of ATF4 leading to the proliferation, invasion, and migration of gastric cancer cells through transcriptionally activating SHH." (PMID 36900220, 2023). "Our findings clearly show that overexpression of ATF4 in gastric cancer cells was associated with more resistance, while knockdown of ATF4 induced re-sensitization." (PMID 22363646, 2012). "We demonstrated that ATF4 overexpression confered the MDR phenotype to gastric cancer cells, while knockdown of ATF4 in the MDR variants induced re-sensitization." (PMID 22363646, 2012). "However, the precise biochemical mechanism underlying ATF4’s contribution to gastric cancer is poorly understood." (PMID 36900220, 2023). "The inhibitor bortezomib (BTZ) restores ATF4 protein levels and effectively overcomes chemoresistance by enhancing gastric cancer cell apoptosis." (PMID 40830338, 2025). "Higher ATF4 expression is significantly correlated with worse overall survival in gastric cancer patients, indicating that ATF4 is an independent prognostic factor." (PMID 39261452, 2024). "The increased expression of ATF4 in gastric cancer has been verified to assess ATF4’s contribution to the emergence of gastric cancer." (PMID 36900220, 2023). "The GCN2/eIF2α/ATF4 pathway can be activated by mitochondria‐derived ROS in gastric cancer cells to increase GSH production." (PMID 37650560, 2023). "We used immunohistochemical (IHC) analysis to examine the expression of ATF4 in 80 pairs of gastric cancer tissues and nearby normal tissues to better understand how ATF4 is expressed in gastric cancer." (PMID 36900220, 2023). "Mechanistically, rescue assays showed that ATF4 regulated gastric cancer cells’ proliferation and invasive ability through SHH." (PMID 36900220, 2023). "ATF4 was considerably higher in gastric cancer than in surrounding tissues when we examined 408 gastric tumors and 211 normal tissues from the GEPIA database." (PMID 36900220, 2023). "By comparing gastric cancer tissues and cells to healthy control tissues and cells, we were able to show that ATF4 is considerably increased in gastric cancer tissues and cancer cells." (PMID 36900220, 2023). "UHMK1 also contributes to purine metabolism reprogramming by regulating the NCOA3/ATF4 axis and significantly promotes gastric cancer development." (PMID 35501324, 2022). "Restoration of ATF4 protein expression by CK1δ or proteasome inhibitor effectively overcame chemoresistance by enhancing apoptosis in gastric cancer cells both in vitro and in vivo." (PMID 34709767, 2021). "Meanwhile, the alteration of ATF4 in gastric cancer cells had little effect on the expression of antioxidant and autophagy related genes before or after DDP incubation (data not shown)." (PMID 34709767, 2021). "In the present study, we reported that ATF4/CHOP axis is downregulated to inhibit drug‐induced apoptosis in chemoresistant gastric cancer." (PMID 34709767, 2021). "In summary, these results confirmed that ATF4 transcriptionally upregulates CHOP to stimulate drug‐induced apoptosis in gastric cancer cells." (PMID 34709767, 2021). "In the present study, we found that activating transcription factor 4 (ATF4) is downregulated in chemoresistant gastric cancer cells." (PMID 34709767, 2021). "In the present study, we found that ATF4 ubiquitination‐dependent proteasomal degradation regulated by CK1δ and βTrCP is important for dynamic and reversible chemoresistance in gastric cancer." (PMID 34709767, 2021). "Meanwhile, we determined ATF4 expression in other gastric cancer cell lines, and measured the cell viability inhibition IC50 of each cell lines to cisplatin (DDP) by MTS assay." (PMID 34709767, 2021). "It was found that the viability inhibition of gastric cancer cells by DDP was correlated to ATF4 expression levels." (PMID 34709767, 2021).
gastric cancer (continued). "Taken together, these findings suggested that ATF4 turnover, which is regulated by CK1δ and βTrCP, is important for dynamic chemoresistance in gastric cancer." (PMID 34709767, 2021). "Taken together, these results indicate that CK1δ stimulates βTrCP‐dependent ATF4 polyubiquitination and subsequent proteasomal degradation to promote chemoresistance in gastric cancer." (PMID 34709767, 2021). "Taken together, these results indicated that ATF4 plays a critical role in repressing chemoresistance in gastric cancer cells." (PMID 34709767, 2021). "The role of activating transcription factor 4 (ATF4) underlying gastric cancer (GC) remains unclear." (PMID 34976799, 2021). "In conclusion, CK1δ stimulates βTrCP‐dependent ATF4 polyubiquitination and subsequent proteasomal degradation to promote chemoresistance in gastric cancer." (PMID 34709767, 2021). "Our findings suggest that enhanced GSH biosynthesis and reduced cisplatin-induced oxidative stress are responsible for the eIF2α–ATF4–xCT-mediated chemoresistance in gastric cancer cells." (PMID 30380689, 2018). "In this study, we demonstrated 7-AB induced ER stress-autophagy cross-talk comes from activation PERK/eIF2/ATF4/CHOP pathway on NCI-N87 gastric cancer cells." (PMID 29587440, 2018). "Recently, mitochondrial dysfunction-induced reactive oxygen species (ROS) production was demonstrated to activate the GCN2–eIF2α–ATF4 pathway and induce cisplatin resistance in human gastric cancer cells." (PMID 30380689, 2018). "In conclusion, we identified for the first time that the ROS-activated GCN2-eIF2α-ATF4-xCT pathway contributes to mitochondrial dysfunction-enhanced cisplatin resistance in human gastric cancer cells." (PMID 27708226, 2016). "In the present study, we found that GCN2, but not PERK, majorly involves in the mitochondrial dysfunction-activated eIF2α-ATF4-xCT pathway and cisplatin resistance in gastric cancer cells." (PMID 27708226, 2016). "We next examined the expressions of ER stress-related proteins, such as p-eIF2α and ATF4 in EF24-treated gastric cancer cells." (PMID 26919110, 2016). "To further investigate the molecular mechanisms involved in ATF4-related MDR of gastric cancer, we also examined MDR1, MRP, Bcl-2, and Bax expression levels in the gastric cancer cells used above." (PMID 22363646, 2012). "Taken together, these results indicate that ATF4 confers a MDR phenotype to gastric cancer cells and that targeting ATF4 provides a method of sensitizing resistant cells to chemical treatments." (PMID 22363646, 2012). "We demonstrated that ATF4 facilitated MDR in gastric cancer cells through direct binding to the SIRT1 promoter, resulting in SIRT1 up-regulation." (PMID 22363646, 2012). "In this study we also showed that the NAD+-dependent histone deacetylase SIRT1 was required for ATF4-induced MDR effect in gastric cancer cells." (PMID 22363646, 2012). "We also showed that ATF4 promoted gastric cancer MDR partly through up-regulating expression of SIRT1." (PMID 22363646, 2012). "In contrast, knockdown of ATF4 with ATF4 specific siRNA led to a down-regulation of SIRT1 in MDR gastric cancer cells." (PMID 22363646, 2012). "In summary, we demonstrate that ATF4 confers a MDR phenotype to gastric cancer cells, and this effect is partly mediated by transactivation of SIRT1 overexpression." (PMID 22363646, 2012). "In this study, we reported that ATF4 was significantly up-regulated in the MDR response of gastric cancer cells compared with parental control cells." (PMID 22363646, 2012). "To address this, we compared the in vitro drug sensitivity in ATF4 stably transfected gastric cancer cells after transfection of SIRT1 siRNA or scrambled siRNA by colony formation and MTT assays." (PMID 22363646, 2012). "Here we show that the protective ability of ATF4 indeed mediates a MDR phenotype in ATF4-overexpressing gastric cancer cell lines in response to chemotherapy." (PMID 22363646, 2012).
gastric cancer (continued). "Moreover, SH003 promotes autophagy-mediated cell death of gastric cancer cells via activating ATF4 and inhibiting G9a under hypoxia." (PMID 38303001, 2024). "The outcomes showed that suppressing ATF4 prevented stomach cancer." (PMID 36900220, 2023). "It is yet unknown how ATF4 contributes to gastric cancer on a cellular level or whether it stimulates the SHH protein through transcription." (PMID 36900220, 2023). "The mechanism of ATF4 as a transcription factor in gastric cancer affecting the Hedgehog pathway remains unclear." (PMID 36900220, 2023). "Furthermore, ATF4 regulates the proliferation, invasion, and migration ability of gastric cancer cells through transcriptional activation of SHH." (PMID 36900220, 2023). "We devised a series of rescue studies to show whether ATF4 controls the proliferation and invasion capacity of gastric cancer cell lines through SHH protein." (PMID 36900220, 2023). "The findings above imply that ATF4 may control gastric cancer cell invasion and proliferation through changing the SHH protein." (PMID 36900220, 2023). "ATF4 positively regulated the proliferation, invasion, and migration of gastric cancer cells." (PMID 36900220, 2023). "ATF4 protein level is negatively correlated to chemoresistance in gastric cancer." (PMID 34709767, 2021). "Thus, downregulation of ATF4 at least partially contributes to cisplatin resistance in gastric cancer cells." (PMID 34709767, 2021). "The ATF4-modulated genes, xCT (a cystine/glutamate anti-transporter), tribbles-related protein 3 (TRB3), heme oxygenase 1 (HO-1), and phosphoenolpyruvate carboxykinase 2 (PCK2), were associated with a poorer prognosis for gastric cancer patients." (PMID 30380689, 2018). "Mitochondrial dysfunction-induced reactive oxygen species (ROS) was demonstrated to activate general control nonderepressible 2 (GCN2)–eukaryotic translation initiation factor 2α (eIF2α)–activating transcription factor-4 (ATF4) pathway-mediated cisplatin resistance of human gastric cancer cells." (PMID 30380689, 2018). "In this study, we used salubrinal (an eIF2α phosphatase inhibitor) to demonstrate that activation of the eIF2α–ATF4 pathway itself may enhance the cisplatin resistance of human gastric cancer cells." (PMID 30380689, 2018). "Moreover, high xCT expression and the activation of the GCN2-eIF2α-ATF4 pathway were observed in cisplatin-resistant gastric cancer cells." (PMID 27708226, 2016). "In conclusion, our results suggested that the ROS-activated GCN2-eIF2α-ATF4-xCT pathway might contribute to mitochondrial dysfunction-enhanced cisplatin resistance and could be a potential target for gastric cancer therapy." (PMID 27708226, 2016). "The GCN2-eIF2α-ATF4-xCT pathway might be a potential drug target for reducing chemoresistance and improving gastric cancer therapy." (PMID 27708226, 2016). "This study is the first report that high levels of ATF4, commonly seen in tumor cells under stressful circumstances, confers gastric cancer cells with a MDR phenotype, and it identifies that this effect is mediated partly by transactivation of SIRT1 expression." (PMID 22363646, 2012). "As ATF4 levels are elevated in MDR gastric cancer cells, we further wanted to determine whether targeting ATF4 could re-sensitize the MDR cell lines." (PMID 22363646, 2012). "We were curious to determine whether SIRT1, which is a stress-related gene critical to MDR development, could be the downstream target of ATF4 responsible for mediating ATF4-induced MDR in gastric cancer cells." (PMID 22363646, 2012). "In this study, we investigate whether ATF4 play a role in gastric cancer MDR and its potential mechanisms." (PMID 22363646, 2012). "However, the Bcl-2/Bax ratio, which was up-regulated in the ATF4-overexpressing cells, was SIRT1-independent, suggesting that SIRT1-independent mechanisms also play a role in the ATF4-induced MDR in gastric cancer cells." (PMID 22363646, 2012).
gastric cancer (continued). "We observed that ATF4 was markedly upregulated in gastric cancer (GC) using immunohistochemistry and Western blotting assays in 80 paraffin-embedded GC samples and 4 fresh samples and para-cancerous tissues." (PMID 36900220, 2023). "Here, we observed that ATF4 was markedly upregulated in gastric cancer (GC) using immunohistochemistry and Western blotting assays in 80 paraffin-embedded GC samples and 4 fresh samples and para-cancerous tissues." (PMID 36900220, 2023). "Immunodeficient BALB/c mice bearing AGS cells that had been stably transfected with the vector or sh-ATF4 lentivirus were utilized to determine the involvement of ATF4 in the carcinogenesis of gastric cancer in vivo in order to confirm further whether ATF4 functions in in vivo models." (PMID 36900220, 2023). "The mechanism of ATF4 as a transcription factor in gastric cancer remains unclear." (PMID 36900220, 2023). "Therefore, we hypothesised that ATF4 stabilisation by BTZ or CK1δ inhibitor could synergise with DDP to enhance its toxicity to gastric cancer." (PMID 34709767, 2021). "Interestingly, the expression of ATF4 protein level was negatively correlated to the reversible drug resistance, indicating that chemoresistance in gastric cancer cells might be attributed to dynamic change of ATF4 protein expression." (PMID 34709767, 2021). "Targeting ATF4 could be a rational strategy to reverse chemoresistance in gastric cancer." (PMID 34709767, 2021). "Therefore, we speculated that restoring ATF4 expression by inhibiting proteasomal degradation or CK1δ activity may be a potential strategy to reverse chemoresistance in gastric cancer." (PMID 34709767, 2021). "However, we confirmed that ATF4 is downregulated in cisplatin‐resistant gastric cancer cells." (PMID 34709767, 2021). "In the present study, we demonstrated that mitochondrial dysfunction induced by low concentrations of oligomycin and antimycin A could increase xCT expression by activating the eIF2α-ATF4 pathway, resulting in cisplatin resistance in three different gastric cancer cell lines." (PMID 27708226, 2016). "And SIRT1 inhibition could partly reverse the gastric cancer MDR phenotype mediated by ATF4." (PMID 22363646, 2012). "Therefore, interventions predicated on disrupting stress-induced ATF4 expression in cancer cells may be effective in circumventing or reversing drug resistance in gastric cancer." (PMID 22363646, 2012). "Our results suggest that SIRT1 might be a downstream mediator of ATF4-induced gastric cancer MDR." (PMID 22363646, 2012). "The biological function of ATF4 in vivo and in vitro by activating SHH has been established, and a more detailed molecular mechanism of ATF4 and SHH regulating the occurrence of gastric cancer should be investigated in the future." (PMID 36900220, 2023). "This study shows that the PF treatment induces the upregulation of GRP78, ATF4, and CHOP, as well as the phosphorylation of PERK and eIF2α via the release of intracellular Ca2+ in a time-dependent manner in gastric cancer cells." (PMID 38140352, 2023). "ATF4 and SHH are significantly expressed in gastric cancer cell lines, as seen in our examination of its expression in Human Gastric Mucosal Epithelial Cells (GES1)." (PMID 36900220, 2023). "Further meta-analysis revealed significant association between higher UTX expression and lower expression of the ATF4 target genes in subsets of acute myeloid leukemia (AML) and gastric cancer patient specimens." (PMID 33633164, 2021). "In gastric cancer, the inhibition of mitochondrial ATP synthesis activates the ISR executor ATF4, but in this case ATF4 was a pro-survival response." (PMID 33291682, 2020). "To verify the essential role of ATF4 in salubrinal-induced cisplatin resistance, we used specific small interfering (si)RNA to knockdown the expression of ATF4 in the AGS gastric cancer cells." (PMID 30380689, 2018).